FOXP3 (forkhead box P3)
Diseases named in the same sentence as FOXP3 in open-access papers (continued):
Sharing a sentence is not in itself a finding about the gene and the disease.
breast carcinoma (continued). "Notably, increased CD8:FOXP3 ratios following NACT are associated with pCR in HER2+ breast cancer patients and even with RFS in TNBC patients with residual disease." (PMID 36139665, 2022). "On the basis of these findings, we conclude that FOXP2 and FOXP3 might act as a potential diagnostic biomarker to differentiate breast cancer from normal normal tissues." (PMID 35614183, 2022). "Furthermore, the infiltration of CD8-positive cells and a high CD8/FOXP3 ratio are associated with a good prognosis in breast cancer." (PMID 35763240, 2022). "A high level of CD8+ (cytotoxic T) lymphocyte infiltration, indicates better patient survival and responses to therapies in basal-like breast cancer, while high density of forkhead box P3 (FoxP3+) regulatory T cells (T-Regs) are frequently linked to poor survival outcomes." (PMID 34376211, 2021). "In our attempt to better understand FOXP3’s inhibitory effect on breast cancer metastasis, we found that MTA1, which is associated with breast cancer metastasis, may be a downstream molecule of FOXP3." (PMID 34307133, 2021). "Tim-3 is not only expressed on IFN-γ-producing T cells, FoxP3+ Treg cells, macrophages, and dendritic cells, but also overexpressed on breast tumor cells, which is associated with poor prognosis in breast cancer." (PMID 34504800, 2021). "Finally, in the luminal A subgroup, high levels of CD3+ and FOXP3+ TILs were associated with shorter recurrence‐free survival, and high counts of FOXP3+ were linked to reduced breast cancer‐specific survival." (PMID 34076969, 2021). "However, it has been reported that FOXP3+ TIL infiltration is strongly associated with adverse clinical outcome in HR-positive breast cancer." (PMID 32216826, 2020). "In CRC patients, a high infiltration of FOXP3+ cells has been linked to an improved prognosis, which is in contrast to what has been shown for many other cancer types e.g. renal cancer and breast cancer." (PMID 32316975, 2020). "Interestingly, the presence of FoxP3+ Tregs in breast cancer patients has been associated with recurrence-free survival." (PMID 32616706, 2020). "High FoxP3+ regulatory T cell (Treg) infiltration is significantly associated with shorter survival in cervical, renal, breast cancers and malignant melanomas, whereas, high FoxP3+ Tregs are associated with improved survival in colorectal, head and neck, and oesophageal cancers." (PMID 30867471, 2019). "High FoxP3+ Tregs infiltration was significantly associated with shorter survival in the most solid tumors, including cervical, renal, melanomas, and breast cancers, whereas FoxP3+ Tregs were associated with improved survival in colorectal, head and neck, and esophageal cancers." (PMID 30926808, 2019). "Furthermore, a relatively high number of FoxP3+ Treg cells, resulting in a decreased CD+ 8/FoxP3+ ratio, is also strongly associated with poor prognosis in breast cancer patients." (PMID 31164094, 2019). "However, other studies have reported statistically significant associations between FOXP3+ and poor survival in breast cancer." (PMID 31391067, 2019). "Therefore, considering that somatic mutations of FOXP3 are common in human breast cancer tissues, it is usually thought that the cytoplasmic localization of FOXP3, resulting from somatic mutation, is associated with the loss of its tumor-suppressive function." (PMID 29549328, 2018). "Additionally, human breast cancer samples and human breast cancer cell lines have a variety of functionally significant mutations and deletions, respectively, in the FOXP3 gene." (PMID 29963231, 2018). "It has been reported that protein–protein interaction could abrogate the tumor-suppressive function of BRCA133, implying that the interaction of FOXP3 with some proteins may result in the loss of its tumor-suppressive properties in breast cancer." (PMID 29549328, 2018).
breast carcinoma (continued). "Finally, CD3, CD8, and FOXP3 mRNA expressions were significantly associated with breast cancer subtypes (Kruskal–Wallis test, P < 0.001, P = 0.032 and P < 0.001, respectively)." (PMID 30240146, 2018). "We suggest that FOXP3 may help maintain normal breast epithelial characteristics through regulation of ZEB2, and loss of FOXP3 in breast cancer cells results in deregulation of ZEB2." (PMID 29963231, 2018). "In addition, we investigated the association between FOXP3+ TILs and some clinicopathological parameters of breast cancer." (PMID 27566250, 2016). "Zuo and colleagues showed a high proportion of somatic mutations and deletions in FOXP3 gene in human breast cancer cells, which may include nuclear localization signals." (PMID 26735887, 2016). "Therefore, we find it necessary to further assess the association between tumor-infiltrating FOXP3+ Tregs and prognosis of breast cancer by conducting a meta-analysis with a large sample size (N = 8666)." (PMID 27566250, 2016). "Our present meta-analysis demonstrated that the detection of FOXP3+ TILs was feasible on core-needle biopsy and excisional specimen and could act as a risk factor for lymph node metastasis in patients with breast cancer." (PMID 26475790, 2015). "Because most of the studies in breast cancer involved mixed cohorts that were largely comprised of ER+ cases, the association between FoxP3+ Tregs and good prognosis in ER– cases may have been obscured by a negative prognostic relationship among ER+ tumors." (PMID 26462617, 2015). "Furthermore, eight studies provided HRs on OS and the pooled results showed that breast cancer patients in the high FOXP3+ TILs group were significantly associated with a poor OS (HR =1.447, 95 % CI [1.037–2.019], p = 0.030)." (PMID 26475790, 2015). "It was reported that FOXP3+ TILs were associated with poor clinical outcome in ER + breast cancer." (PMID 25193543, 2014). "Recent studies have reported that FOXP3+ T-cell infiltration is associated with poor clinical outcome, whereas others found no significant prognostic role for FOXP3+ infiltration in a large series of breast cancers." (PMID 25193543, 2014). "In addition, the loss of expression and somatic mutation of the human FOXP3 gene has been identified in human prostate and breast cancers." (PMID 25364468, 2014). "In ER + breast cancer, high FOXP3+ TILs were significantly associated with poor clinical outcome." (PMID 25193543, 2014). "In fact, widespread deletions and somatic mutations of FOXP3 were observed in breast cancer tissue." (PMID 24155921, 2013). "In breast cancer, an increase in the Treg population, both in peripheral blood and tumour tissue, was also reported and a recent study demonstrated a correlation between intratumoural infiltration of FOXP3+ Tregs in breast cancer and the risk of late relapse." (PMID 21818290, 2011). "In breast cancer, an increase in Tregs population both in peripheral blood and tumor tissues was also reported and a recent study demonstrated a significant intratumoral infiltration of FOXP3+ Tregs in high-risk breast cancer patients and those at risk of late relapse." (PMID 18294387, 2008). "The association of FOXP3+ Tregs with bad prognostic factors may suggest a contribution of Tregs infiltrating breast cancer tissues to tumor escape from the immune system as their depletion lead to tumor rejection in animal models." (PMID 18294387, 2008). "MicroRNA-200c (miR-200c) is a known tumor suppressor that inhibits epithelial-mesenchymal transition (EMT), while FOXP3, a transcription factor typically associated with regulatory T cells, is aberrantly expressed in breast cancer cells and may contribute to tumor progression." (PMID 41691218, 2026).
breast carcinoma (continued). "However, in breast cancer patients, the expression of chemokine receptor CCR4 in tumor infiltrating Tregs is higher than that in peripheral Tregs, The expression of FOXP3 in breast cancer tissue is higher than that in normal tissue, and overexpression of FOXP3 is associated with better prognosis." (PMID 38919615, 2024). "Regarding the TILs, increased infiltration of FoxP3+ Tregs was associated with improved OS in colorectal, head and neck, and esophageal cancer, whereas in melanoma, lung, cervical, renal, hepatocellular, gastric, and breast cancers, it was linked with shorter OS." (PMID 36980787, 2023). "However, the malignant transformation of breast cancer is associated with the loss of Foxp3 expression, suggesting that Foxp3 may be a tumor suppressor." (PMID 35345443, 2022). "Methylation at various CpG present in the upstream promoter area of FOXP3 gene was observed in 73 cases (73/140, 52.14%) and, once linked with clinical parameters, revealed a significant association with the Nottingham histological grades 1 and 2 type tumors of breast cancer patients (0.031)." (PMID 34938323, 2021). "In addition, deletions and mutations of FOXP3 have been found in human breast cancer samples." (PMID 30011797, 2018). "Additionally, these authors postulated that FOXP3 gene may be involved with the hereditary breast cancer form, with high penetrance mutations." (PMID 24877082, 2014). "Targeting the miR-200c/FOXP3 axis presents a novel and promising therapeutic approach for advanced breast cancer." (PMID 41691218, 2026). "In human breast cancer fibroblasts, enrichment of CAF-S1 subsets in breast tumors is associated with accumulation of FoxP3+ Tregs." (PMID 40216744, 2025). "One study found significant correlations between RCB classes and TIL CD8/FOXP3 ratio in TN breast cancer." (PMID 39285068, 2025). "Conversely, some views suggest that high expression of the FOXP3 protein in breast cancer and hepatocellular carcinoma exerts tumor-suppressive effects." (PMID 40587482, 2025). "Further research has shown that ADQ reshapes the immunosuppressive TME of breast cancer and inhibits breast cancer metastasis by reducing Treg differentiation and infiltration through suppression of the NF-κB/Foxp3 pathway." (PMID 41458964, 2025). "Tregs, identified by their expression of CD4, CD25, and FOXP3, serve as key suppressors of anti-tumor immune responses in the breast cancer TIME." (PMID 41550427, 2025). "For example, in breast tumors, different states of ER caused Tregs to have different prognostic effects, mainly when FoxP3+ Tregs were highly infiltrated, while ER- breast cancer had a good prognosis and ER- breast cancer had a poor prognosis." (PMID 40216744, 2025). "Ultimately, this activated CD45+CD8+ effector T cells and incapacitated CD4+CD25+Foxp3+ Tregs, transforming “cold” into “hot” tumors and enhancing the anti‐tumor effect of chemotherapeutic agents in breast cancer in vivo." (PMID 39585774, 2025). "Here, worse outcomes were mainly found in studies focused on intra-tumoral FOXP3 expression, in all breast cancer subtypes." (PMID 39904885, 2025). "Other types of immune cells used as a prognostic marker for breast cancer patients include Forkhead Box P3-positive lymphocytes (Tregs), Natural Killer (NK) cells, and macrophages." (PMID 39904885, 2025). "An increase in Foxp3 expression has been observed even in sentinel lymph nodes of breast cancer patients with molecular micro metastasis, indicating that Treg accumulation happens early during lymph node colonization." (PMID 40730190, 2025). "Treatment with ASmA in the breast cancer model induced a statistically significant reduction in FoxP3+ cells compared to the DMBA group." (PMID 40247360, 2025). "Future research should continue to delve deeply into the complex relationship between Foxp3 and breast cancer." (PMID 39329710, 2024).
breast carcinoma (continued). "While others reported FoxP3 was a cancer suppressor gene in breast cancer, prostate cancer, gastric cancer, as well as HCC." (PMID 39073490, 2024). "In breast cancer, EGFR positivity has been associated with increased FOXP3+ regulatory T cells, which are known to suppress antitumour immunity." (PMID 38744099, 2024). "In summary, anisomycin, a cellular stress inducer, activated c‐Jun and ATF2 heterodimers to stimulate FOXP3 expression in mouse and human breast cancer cell lines." (PMID 38827026, 2024). "A study with a mouse 4T1 model of breast cancer demonstrated that the secretion of IL-10 by B lymphocytes acts in a TGF-β-dependent manner to promote the conversion of naive CD4+ T cells to Foxp3+ Tregs." (PMID 38533507, 2024). "In another study of breast cancer, pDCs inhibited the proliferation of FOXP3+ Treg cells by IFN-α, providing evidence for pDCs regular CD4+ T cell function.." (PMID 39198425, 2024). "Given that CD4 + CD25 + Foxp3 + is the predominant Treg phenotype, we utilized hospital cohort breast cancer samples for IHC testing of CCL11, CD4, and Foxp3 proteins." (PMID 38305920, 2024). "The majority of the tumors were discovered to be mammary carcinomas with overexpressed HER‐2/ErbB2 and inactivated wild‐type FOXP3 alleles." (PMID 38827026, 2024). "The study conducted by Kuehnemuth and co-authors (2018) found a strong correlation between a high presence of CCR8+FOXP3+ Tregs and a worse prognosis in breast cancer patients." (PMID 38730579, 2024). "It was suggested that inhibiting Foxp3 acetylation by using p300 inhibitors further reduced Treg activity and enhanced anti-breast cancer function in transgenic animals." (PMID 39329710, 2024). "FOXP3 is expressed in epithelial tissue of breast, lung and prostate where it acts as a tumor-suppressor gene, as proven by the presence of genetic alteration in FOXP3 in human breast cancer samples." (PMID 39475830, 2024). "This study focused on the role of Foxp3+ cells in canine mammary carcinoma in three areas: the intratumoral compartment, the adjacent stroma, and the distant stroma." (PMID 36766393, 2023). "The high CCL11 level was shown to increase the proportion of immunosuppressive CD4+CD25+Foxp3+ Tregs in a breast cancer model, indicating the pro-tumoral effect of the IL-4/CCL11 interaction." (PMID 37445941, 2023). "FoxP3 was first reported in human pancreatic cancer cells, and later, it was also detected in breast cancer, prostate cancer, non-small cell lung cancer (NSCLC), gastric cancer, thyroid cancer, melanoma, and hepatocellular carcinoma." (PMID 37569676, 2023). "Liu et al37 have reported that FOXP3+ regulatory TILs are a poor prognostic indicator in ER+ breast cancer, but a favorable prognostic factor in the HER2+/ER‐ subtype." (PMID 38151972, 2023). "In breast cancer, sympathetic denervation surprisingly downregulated the expression of immune checkpoint molecules (PD-1, PD-L1, and FOXP3)." (PMID 37215113, 2023). "Enhanced Treg frequencies in the circulation and increased FOXP3 expression in metastatic lesions were observed in breast cancer patients upon blockade of PD-1/PD-L1-axis." (PMID 37089449, 2023). "Here we assessed Foxp3 tumor intrinsic effects in experimental breast cancer using a Foxp3 binder peptide (P60) that impairs Foxp3 nuclear translocation." (PMID 37766222, 2023). "Augmented Treg numbers during chemotherapy also clarifies why higher FOXP3 expression correlates with lower RFS in NACT-treated breast cancer patients as observed in our in-silico data." (PMID 38038865, 2023). "Our findings confirmed that Foxp3+ cells were significantly higher in canine mammary carcinomas compared to adenomas." (PMID 36766393, 2023). "The different roles of TILs in ER + /HER2− compared with those in HER2 + or TN breast cancers seem to stem from the composition of subsets of T cells, including FOXP3 + T cells, which are more abundant in ER + than in ER- breast cancers." (PMID 37115435, 2023).
breast carcinoma (continued). "In this cohort of 139 HER2 + breast cancer cases, we found that the numbers of FoxP3 + TILs and CD8 + mTILs correlated positively with each other and with TAMs." (PMID 37428418, 2023). "In fact, high Foxp3 cell counts have been reported to positively correlate with the rate of lymphovascular invasion in patients with breast cancer, and we believe that our results support this finding." (PMID 37958412, 2023). "In breast cancer, Foxp3+ T cells have been reported to promote tumor invasion and metastasis, and CD8 is a favorable prognostic factor." (PMID 37958412, 2023). "Another member of the FOX family, FOXP3, has been reported to inhibit breast cancer angiogenesis by downregulating VEGF expression." (PMID 36901702, 2023). "The expression of CD8, Foxp3, and PD-L1 in the tumor microenvironment is regarded as predictors for prognosis and response markers to immunotherapy in melanoma, breast cancer, NSCLC, and gastric cancer." (PMID 37205112, 2023). "Foxp3+ cell counts were evaluated by immunohistochemistry in 59 canine mammary tumors, 20 adenomas, and 39 carcinomas in three different compartments: intratumoral, within the adjacent stroma, and in the distant stroma." (PMID 36766393, 2023). "Regarding mammary cancer, human studies on the role of FoxP3 have highlighted contrasting results, and the veterinary literature is poor." (PMID 36766393, 2023). "Both Western blotting and reverse-transcription-quantitative PCR demonstrated that FOXP3 increased the production of PDCD4 in mammary tumor cells." (PMID 37626655, 2023). "FoxP3 cannot only be expressed by lymphocytes, but also by tumor cells as has, for example, been observed in breast cancer." (PMID 36098901, 2022). "In human breast cancer HCC202 cells, which express a synonymous heterozygous mutation in the coding region of FOXP3, simultaneous silencing of XIST from XCI led to enhanced and prolonged FOXP3 activation." (PMID 35130925, 2022). "Our results showed that FOXP2 or FOXP3 had a significantly high AUC value in the detection of breast cancer, with 96.8% or 95.7% in accuracy respectively." (PMID 35614183, 2022). "In both the breast carcinoma and melanoma models, FOXP3 ablation significantly reduced tumor volume and mass." (PMID 35222362, 2022). "And lncRNA DRAIC was activated by FOXP3 in breast cancer and promoted cell proliferation in SKBR3 and MDA-MB-231 cells via sponging miR-432-5p to increase SLBP levels." (PMID 35992823, 2022). "The FOXP3+CCR4+ Tregs from breast cancer patients’ peripheral circulation infiltrate tumor site in response to TME-secreted CCL17 and CCL22." (PMID 35222362, 2022). "A lot of studies prove, FoxP3 is expressed in a variety of tumors such as colon cancer, pancreatic cancer, liver cancer, bladder cancer, breast cancer, melanoma, lung cancer, prostate cancer, and glioma." (PMID 35783156, 2022). "Another significant result of this study revealed that FOXP3 expression predicted the breast cancer cells’ response to anticancer drugs, whereas FOXP1, FOXP2 and FOXP4 did not predict." (PMID 35614183, 2022). "In both mammary carcinoma- and melanoma-bearing mice, ablation of FOXP3 reduces the generation of CCR4+ Tregs and hence their infiltration into the tumor site." (PMID 35222362, 2022). "After the injection of UA-liposomes in a murine breast cancer model, they reached the tumor tissue and reduced IL-10 and IL-6 secretion as well as Foxp3+ phenotypic Tregs cells by inhibiting STAT5 phosphorylation." (PMID 35335881, 2022). "By secreting CXCL12, CAFs attract conventional CD4+ T cell migration through its receptor-CXCR4 and promotes their differentiation into Foxp3+ regulatory T cells to create an immunosuppressive environment in human breast cancer." (PMID 35853880, 2022).